AR (androgen receptor)
Diseases named in the same sentence as AR in open-access papers (continued):
Sharing a sentence is not in itself a finding about the gene and the disease.
prostate tumors (continued). "Several AR alternative splicing isoforms have been detected in clinical samples, within the normal prostate, in primary prostate tumors, as well as in metastases." (PMID 35740556, 2022). "In this context, well-differentiated luminal cells were predominant in canine prostate tumors since most of them are capable of expressing AR and CK8/18." (PMID 35681707, 2022). "The Androgen receptor (AR) signaling is a major pathway that sustains local and metastatic prostate tumor growth." (PMID 35966880, 2022). "Among the EGFR family, HER2 tyrosine kinase modulates AR signaling activity and promotes androgen-independent prostate tumor growth in vitro and in vivo." (PMID 35740556, 2022). "Following the administration of therapies that target androgen receptor (AR) signaling, prostate tumors progress to castration-resistant forms that are less dependent on circulating androgen levels." (PMID 36175875, 2022). "Inhibition of tumor growth in preclinical models of both castration-sensitive and resistant AR-driven prostate tumors." (PMID 36358940, 2022). "Akt enhances the androgen-independent survival of prostate tumor cells by regulating AR expression and activation." (PMID 35335890, 2022). "We found that advanced PCa cells utilize an alternative mechanism of ATF6-mediated UPR, thus simplifying stress response and promoting the maturation of proteins responsible for the growth of the prostate tumor, including those involved in AR signaling." (PMID 34521429, 2021). "AR, a functional androgen receptor, is a therapeutic target used in cancers, such as prostate tumor." (PMID 34311656, 2021). "In prostate tumours, AR-mediated metabolic reprogramming is responsible for a metabolic shift to oxidative phosphorylation coupled with a loss of zinc transporter during oncogenic transformation." (PMID 34262149, 2021). "Our results suggest that AR positively regulates eIF5A2 expression in androgen-dependent cells, and stimulation of AR expression and signaling in prostate tumors promotes PCa metastasis by EMT induction and upregulation of eIF5A2." (PMID 34864817, 2021). "The androgen receptor (AR) is a key transcription factor that promotes luminal cell fates and AR activity is necessary for the growth of all early stage prostate tumors." (PMID 34314419, 2021). "AR signaling is constantly active and provides the basis for the progression and survival of prostate tumor cells." (PMID 33805919, 2021). "Overall, this collection of PDXs spans the clinical heterogeneity of prostate tumors from diagnosis to death, including a range of adenocarcinoma (AR-positive), neuroendocrine (AR-null), and mixed phenotypes." (PMID 34413304, 2021). "Since PCa cells require androgen receptor (AR) signaling for their growth and survival, androgen withdrawal results in the regression of prostate tumors." (PMID 35366279, 2021). "Here, we highlight the role of PI3K-AKT-mTOR signaling as a resistance mechanism for PCa therapy and illustrate the transition of prostate tumor from AR signaling-dependent to PI3K-AKT-mTOR pathway-dependent." (PMID 34681745, 2021). "The molecular mechanisms driving the persistence of prostate tumour cells during acute AR signalling inhibition appear distinct from those responsible for breakthrough, progressive castration resistant disease." (PMID 35008330, 2021). "ARVib significantly inhibits resistant prostate tumor growth and improves Enza treatment in vitro and in vivo, suggesting a clinical potential for development as an AR/AR-V7 degrader to treat resistant CRPC." (PMID 34272475, 2021). "Semiquantitative analysis of the Western blot densitometry showed that expression levels of full-length AR (AR-FL) were lower in prostate tumors compared to normal prostate." (PMID 34439133, 2021). "In the disease spectrum of PCa, patients with metastatic disease have shown decreased AR stromal expression compared to that in the corresponding primary prostate tumor." (PMID 33805919, 2021).
prostate tumors (continued). "Alternative splicing of the AR gene is much more predominant in androgen-driven prostate tumours that have undergone anti-androgen therapy." (PMID 33993099, 2021). "We illustrate the transition of the prostate tumor from AR signaling-dependent towards PI3K-AKT-mTOR pathway-dependent." (PMID 34681745, 2021). "Alternative transcripts were recurrently identified in EGFR (i.e., vIII, vIVb) within CNS tumors in AR (e.g., v7) within prostate tumors, and in MET (e.g., exon 14 skipping) within breast and lung (data not shown) tumors." (PMID 33889297, 2021). "Prostate tumors inevitably escape AR inhibition through reactivation of AR signaling or, increasingly, via lineage plasticity." (PMID 33785741, 2021). "Examination of serial tissue sections of prostate tumors from control and apalutamide-treated mice were stained with proliferation and apoptosis markers as well as AR, p-AKTpS473, p-PRAS40, p-ERK and pSTAT3pY705." (PMID 34439133, 2021). "PCai1 cells, which were established initially from castration-resistant prostate tumors, can be grown in androgen-free medium conditions, and the normal AR function is maintained." (PMID 34298624, 2021). "Nevertheless, primary prostatic adenocarcinomas, the most frequent type of prostate tumors, have a predominantly luminal phenotype characterized by androgen receptor (AR) positivity and active AR signaling." (PMID 31936761, 2020). "Recurrently mutated in primary and metastatic prostate tumors, FOXA1 encodes a pioneer transcription factor involved in disease onset and progression through both androgen receptor-dependent and androgen receptor-independent mechanisms." (PMID 31974375, 2020). "A TMA containing prostate tumor sections from a cohort of 410 PCa patients was evaluated for AR and AR-V7 protein expression by immunohistochemistry (IHC) using an AR-V7 monoclonal antibody as described in the methods section." (PMID 32947898, 2020). "In our study, SP-2509 diminished cell proliferation in all prostate tumor cells but was most dramatic in AR-positive tumor cells." (PMID 31901895, 2020). "Further studies will be necessary to predict and validate the immunogenicity of neoepitopes generated in response to AR inhibitors, including identification of T cells infiltrating prostate tumors specific to predicted neoepitopes." (PMID 32820253, 2020). "NCL expression was knocked-down by 80% with two siRNAs in three human AR-positive prostate tumor cell lines, LNCaP, VCaP, and C4-2." (PMID 32477465, 2020). "AR, a member of the nuclear receptor superfamily, is a ligand-dependent transcription factor that regulates the transcription of genes involved in prostate tumor growth and survival." (PMID 32296610, 2020). "Further, earlier studies from our and other groups explored PMEAP1 gene isoforms (a and b) in the initiation and development of prostate tumors via interrupting AR and/or TGF-β signaling." (PMID 32064040, 2020). "Initially, the growth of prostate tumors is dependent on androgens that activate the androgen receptor (AR) in tumor cells, and promote their survival and proliferation." (PMID 32404918, 2020). "The prostatic tumor cells plasticity is involved in resistance to hormone-therapy, allowing these cells to survive despite androgen receptor inhibition." (PMID 33224888, 2020). "Carbidopa, as an inhibitor of DDC, can suppress DDC coactivation of AR and retard prostate tumor growth." (PMID 32404918, 2020). "The PMEPA1 silencing conferred the development of resistance to AR inhibitors in vitro, as well as promoted the androgen independent xenograft growth of prostate tumor in nude mice." (PMID 32064040, 2020). "Another example was that AR (androgen receptor)-amplified prostate tumor organoids were sensitive to the inhibitor enzalutamide." (PMID 32977530, 2020).
prostate tumors (continued). "With the recent introduction of new generation potent AR pathway inhibitors, such as abiraterone and enzalutamide, an increasing number of prostate tumors acquire NEPC features and transdifferentiates in the so-called “therapy emergent NEPC”." (PMID 32041153, 2020). "Further analysis using ChIP has established that CAMKK2 is indeed a direct target of the AR in prostate tumor biopsies from human patients." (PMID 32927797, 2020). "The majority of prostate tumors are adenocarcinomas, which derive from the transformation of glandular prostatic epithelial cells and rely on the influence of the androgens-androgen receptor (AR) axis for development and progression." (PMID 32041153, 2020). "The proliferation of prostate tumor cells relies on the transcriptional activity of the androgen receptor (AR), which closely depends on the levels of its ligands testosterone or dihydrotestosterone (DHT)." (PMID 32560058, 2020). "Prostate tumors with high androgen receptor (AR) transcriptional output have increased expression of DNA repair genes in general, and base excision repair (BER) associated proteins in particular." (PMID 32123273, 2020). "In human prostate tumors, an AR and PARG functional interaction is supported by highly significant positive Spearman correlations between AR and PARG mRNA levels: r = 0.38, p = 1.00e-1755, r = 0.33, p = 5.30e-942, r = 0.41, p = 4.15e-21 (TCGA, Provisional)." (PMID 32123273, 2020). "This strategy comes from the fact that the primary prostate tumor is mostly made up of Androgen Receptor-positive (AR+) cancer cells, which are initially androgen-dependent." (PMID 33062666, 2020). "(F) AR ChIP-sequencing data from VCaP cells, normal human prostate and primary human prostate tumor specimens." (PMID 32686647, 2020). "Of these, we prioritized GREB1 for further characterization because GREB1 mRNA levels are increased in primary prostate tumors that have high AR activity." (PMID 30644358, 2019). "Even in the resistant prostate tumors, AR signaling is considered to play an active role as evidenced by PSA relapse and other clinical data." (PMID 31877956, 2019). "In PtenL/L:PB-Cre4 mice, most prostatic tumor cells were stained positively for E-cadherin, AR, and CK8 (Fig 6F2, 6F3 and 6F5, respectively) while CK5 positive cells were mainly observed lining the basement membrane areas (Fig 6F6)." (PMID 31658259, 2019). "In conclusion, this study identified distinct androgen-responsive genes in both ETS− and ETS+ prostate tumors, and validated 131 AR-target genes that are regulated in an ETS-specific fashion." (PMID 30367117, 2019). "Initially, growth of prostate tumours is dependent on circulating androgens activating the androgen receptor (AR)." (PMID 31043708, 2019). "Ligand-induced activation of AR upregulates the autophosphorylation of Src, whereas culture of a prostate tumor cell line under androgen ablation conditions dramatically attenuates Src autophosphorylation." (PMID 31537808, 2019). "(F) The correlation between RNA levels of GREB1, GHRHR and KLF8 and AR score in 333 TCGA primary prostate tumors were analyzed using Pearson’s correlation analysis (r)." (PMID 30644358, 2019). "Since ETS− and ETS+ prostate tumors differentially expressed distinct sets of androgen response pathway genes, we assessed if the AR directs distinct transcriptional programs in PCa based on ETS status." (PMID 30367117, 2019). "In enzalutamide-resistant prostate tumors, upregulation of GR was described as a resistance mechanism where the receptor was able to substitute for AR and drive expression of a subset of target genes." (PMID 31855178, 2019). "Specifically, AR gene amplification or upregulation of the AR gene expression appears along with other genetic and epigenetic alterations in human prostate tumor tissues." (PMID 30677079, 2019).
prostate tumors (continued). "To test if the presence of androgen had any effect on response of AR to CK2 modulation in prostate tumor cells, we examined the effect of 80 μM TBB on C4-2B and 22Rv1 cells cultured in androgen-free media for a total of 72 h and treated with TBB for 48 h." (PMID 31197122, 2019). "The present study is designed to determine if aPPD can inhibit AR-positive castration-resistant C4-2 xenograft prostate tumors." (PMID 29765513, 2018). "Cumulatively, these data indicate that by integrative analyses, we revealed a subclass of prostate tumors, hallmarked by low AR activity, neuroendocrine-like gene expression, minimal copy number alterations, and few mutations." (PMID 30464211, 2018). "Clinically, HSP70 expression is upregulated and correlated with AR/AR-V7 levels in high Gleason score prostate tumors." (PMID 30446660, 2018). "Further, we observed a positive correlation between Ki67 immunostaining and androgen signaling in bicalutamide‐treated PDEs, consistent with the effect of bicalutamide on prostate tumor PDE proliferation being AR‐mediated." (PMID 30117261, 2018). "Despite castrate levels of androgens, AR signaling is still active under these conditions and human prostate tumors express AR." (PMID 30036938, 2018). "This evidence provides proof of principle that activated AR signaling in prostate tumor cells can counteract the tumor-suppressor function of TGF-β towards emergence of CRPC." (PMID 29562686, 2018). "Our analysis of metastases in the Krt8-CreERT2 model suggests that larger lung tumors resemble the primary prostate tumors, expressing the AR at varying levels and Trp63 in a proportion of the cells." (PMID 29782499, 2018). "One such resistance mechanism is AR overexpression in prostate tumor cells, which is replicated in the VCaP and LNCaP/AR cell lines through gene amplification and genetically engineered stable overexpression, respectively." (PMID 30271980, 2018). "Androgens are one critical factor for the development and progression of prostate tumors and are the main therapeutic target consisting of androgen depletion or androgen receptor (AR) blocking in advanced and metastatic prostate cancer disease." (PMID 30001402, 2018). "In castrate-resistant prostate tumors a dynamic AR/β-catenin crosstalk leads to their increased nuclear co-localization and interaction." (PMID 28430640, 2017). "The differential AR binding at this enhancer in normal versus cancer, despite comparable levels of AR expression, is consistent with extensive reprogramming of the AR cistrome reported in human prostate tumors." (PMID 28891793, 2017). "Appreciable levels of CCDC6 and USP7 proteins have been observed in a series of prostate tumor cell lines independently of the expression of androgen receptor." (PMID 28415632, 2017). "The development of potent androgen synthesis inhibitors and AR antagonists has remained the mainstay strategy in managing prostate tumors." (PMID 28852180, 2017). "Nonetheless, the vast majority of androgen and androgen receptor (AR) research has been focussed on epithelial cancer cells because of the response of these cells, and prostate tumours, to androgen deprivation." (PMID 28117763, 2017). "Elevated AR-V7 levels have also been detected in circulating prostate tumor cells isolated from patients that are resistant to enzalutamide and abiraterone acetate, two relatively new drugs that target the AR signaling pathway." (PMID 29181019, 2017). "AR-FL within the epithelial derived tumor cells promotes growth of early stage and advanced prostate tumors." (PMID 29181019, 2017). "Because NRIP expression is correlated with AR expression in human prostate tumors; we were interested in understanding the mechanism for positive correlation between NRIP and AR." (PMID 28212551, 2017).
prostate tumors (continued). "Responsible for the physiological growth and development of prostate gland, and for the development and progression of prostate tumors, androgens display their biological activity by binding and consequently activating the androgen receptor (AR)." (PMID 28430640, 2017). "FAM84B CNVs (largely amplification) were detected in 8% (37/492) of PCs, while AR CNVs occurred in 1% of prostate tumors." (PMID 28186973, 2017). "We then selected LAPC-4 prostate tumor cells since they express a wild-type AR and can form tumors in mice." (PMID 28182747, 2017). "Our published data have shown that sGCα1 is an AR target gene that is over-expressed in prostate tumors at both the mRNA and protein levels, while expression of sGCβ1, its dimerization partner to form the sGC enzyme, is not significantly elevated." (PMID 28859127, 2017). "It is well-known that androgen receptor (AR) plays a pivotal role in a vast majority of prostate tumors." (PMID 29206234, 2017). "In contrast to previous studies in melanoma and hepatocellular carcinoma reporting reduced ING3 levels in aggressive cancers, our analyses of primary prostate tumors showed that high levels of ING3 predict poorer outcome in patients with low AR levels." (PMID 28511652, 2017). "In contrast, the AR is a survival factor that promotes the proliferation of luminal cellsthat constitute more than 99% of prostate tumor epithelial cells." (PMID 28212551, 2017). "To work towards a single cell dynamic assay to query prostate tumor cells directly, we developed and characterized a bioluminescence microscopy technique to measure androgen receptor (AR) activity in single cells upon antiandrogen treatment." (PMID 27678181, 2016). "Androgen receptor (AR) is a nuclear receptor that has been recognized as a major factor involved in prostate tumor genesis." (PMID 26787499, 2016). "Proteins involved in protein trafficking were targeted for siRNA-mediated knockdown because a functional relationship between this class of proteins and AR-dependent transcription has yet to be fully established at the molecular level in prostate tumor cells." (PMID 27365400, 2016). "N6L treatment of prostate tumor cells led to inhibition of NPM1 phosphorylation in conjunction with inhibition of AR activity." (PMID 26993766, 2016). "Collectively, this study provides a bioanalytical strategy to validate the AR-interactome and define novel AR-interacting proteins involved in ligand-mediated AR activation in prostate tumor cells." (PMID 27365400, 2016). "Our findings suggest that androgen-mediated AR activation is coupled to a number of PPIs between AR and various functional protein complexes in the cytosolic compartment of prostate tumor cells." (PMID 27365400, 2016). "Assuming that MDM2 promotes AR protein degradation/turnover, our results suggest that this process is required for normal ligand-dependent AR transcriptional activity in prostate tumor cells." (PMID 27365400, 2016). "As expected, more in depth molecular studies will be required to establish a direct functional link between protein trafficking and AR-mediated transcription in prostate tumor cells." (PMID 27365400, 2016). "Although miR-31 is decreased in prostate tumors relative to adjacent normal tissue, there are varying levels of decreased miR-31 expression in androgen receptor (AR)-positive PCa cells relative to AR-negative cells." (PMID 26734997, 2016). "Conversely, ERG has been reported to indirectly reprogram the androgen receptor cistrome in prostate tumors." (PMID 26938745, 2016). "Regardless of these incongruent findings, the siRNA luciferase screen represents a powerful tool for identifying modulators of AR-mediated transcription in LNCaP prostate tumor cells." (PMID 27365400, 2016). "In summary, this study describes a cellular system and bioanalytical workflow for defining ligand-dependent AR-interactome networks in human prostate tumor cells." (PMID 27365400, 2016).